SLC39A2 (solute carrier family 39 member 2)
Description:
Transporter for the divalent cation Zn(2+). Mediates the influx of Zn(2+) into cells from extracellular space. The Zn(2+) uniporter activity is independent of H(+)-driving force, but is modulated by extracellular pH and membrane potential. Also transports other divalent cations Zn(2+), Cd2(+), Cu2(+), Co2(+) in the order of decreasing affinity, respectively. In the skin, aids in the differentiation of keratinocytes in the epidermis (By similarity).
Synonyms: ZIP-2; ZIP2; 6A1; ETI-1
Tractability: Antibody: UniProt places it where antibodies can reach, with high confidence; its Gene Ontology location is reachable by antibodies, with high confidence; UniProt predicts a signal peptide or a membrane-spanning region; the Human Protein Atlas places it where antibodies can reach.
Gene: Protein-coding gene on chromosome 14 (20,999,255 to 21,001,871, forward strand). Ensembl gene ENSG00000165794.
Subcellular location: Cell membrane
Subcellular location (Human Protein Atlas): Plasma membrane; Cytoplasmic bodies
Pathways (Reactome):
Transport of small molecules: Zinc influx into cells by the SLC39 gene family
Gene Ontology:
Molecular function: metal ion transmembrane transporter activity; protein binding; zinc ion transmembrane transporter activity
Biological process: cadmium ion transmembrane transport; zinc ion transmembrane transport; zinc ion import across plasma membrane; zinc ion transport; keratinocyte differentiation; metal ion transport; transmembrane transport
Cellular component: cytoplasmic vesicle; plasma membrane; membrane
Genetic constraint (gnomAD): Loss-of-function variants: 14 observed, 15.63 expected, observed/expected ratio (o/e) 0.9, 90% interval 0.59 to 1.4. The upper end of that interval is the gene's LOEUF score, 1.4, which puts it in group 5 of 6, group 1 being the genes least tolerant of losing a copy. Missense variants: 366 observed, 375.65 expected, observed/expected ratio (o/e) 0.97, 90% interval 0.89 to 1.06. Synonymous variants: 151 observed, 157.64 expected, observed/expected ratio (o/e) 0.96, 90% interval 0.84 to 1.1.
Homologues: Orthologues: chimpanzee SLC39A2 (99% identical), macaque SLC39A2 (96% identical), pig SLC39A2 (82% identical), rabbit SLC39A2 (80% identical), dog SLC39A2 (80% identical), mouse Slc39a2 (78% identical), rat Slc39a2 (77% identical), guinea pig Slc39a2 (75% identical), tropical clawed frog slc39a2 (43% identical), Caenorhabditis elegans zipt-2.1 (28% identical), Caenorhabditis elegans zipt-2.2 (25% identical). Paralogues in human: SLC39A1 (35% identical), SLC39A3 (28% identical).
Diseases named in the same sentence as SLC39A2 in open-access papers:
SLC39A2 is named in the same sentence as 13 diseases in open-access papers, as found by Europe PMC text mining. Sharing a sentence is not in itself a finding about the gene and the disease. The quoted sentences say what the papers report.
heart failure (2 papers, 2021 to 2022). Inability of the heart to pump blood at an adequate rate to meet tissue metabolic requirements. "Leveraging Slc39a2 to target intracellular zinc metabolism might be a novel strategy to treat cardiac hypertrophy and heart failure." (PMID 34790705, 2021). "Recent research has identified the involvement of SLC39A2 (ZIP2) in the development of cardiac hypertrophy and heart failure." (PMID 35805904, 2022).
prostate carcinoma (2 papers, 2020 to 2021). A carcinoma that arises from epithelial cells of the prostate gland. "Recent studies have suggested that low SLC39A1, SLC39A2 and SLC39A3 expression in prostate cancer, low SLC39A3 and high SLC39A4 expression in pancreatic cancer." (PMID 34615436, 2021). "Low levels of Zn have been detected in serum and tumor tissues of patients with prostate cancer, and downregulated expression of SLC39A1, SLC39A2 and SLC39A3 has been demonstrated." (PMID 32744318, 2020).
bladder cancer (1 paper, 2025). "For example, a pan-cancer TCGA analysis found that tumor overexpression of SLC39A3, SLC39A5, and SLC39A11 was associated with better overall survival after bladder cancer diagnosis, whereas tumor overexpression of SLC39A2, SLC39A8, SLC39A9, and SLC39A14 was associated with poorer survival." (PMID 39789109, 2025).
breast carcinoma (1 paper, 2021). "Our findings were consistent with those of the previous study, in that high mRNA expression levels of SLC39A6 and SLC39A14 indicated favorable OS, but upregulated SLC39A2-5, SLC39A7, and SLC39A12-13 were associated with poor OS in the patients with breast carcinoma." (PMID 34925450, 2021).
cardiac hypertrophy (1 paper, 2021). "Taken together, our study unveils the molecular mechanism for the dynamic regulation of Slc39a2 during cardiac hypertrophy, and demonstrates that SLC39A2-mediated zinc homeostasis contributes to the remodeling of innate immune signaling in cardiomyocyte hypertrophy." (PMID 34790705, 2021). "However, whether and how SLC39A2 affects the development of cardiac hypertrophy remain unexplored." (PMID 34790705, 2021).
gastric cancer (1 paper, 2021). A primary or metastatic malignant neoplasm involving the stomach. "Higher expression of SLC39A1, 5–7, and 9 indicated better OS, FPS, and PPS, and increased SLC39A2–4, 8, and SLC39A10 expression indicated poor OS, FP, and PPS in the patients with gastric cancer." (PMID 34925450, 2021).
lymph node metastasis (1 paper, 2020). "For patients with positive lymph node metastasis, SLC39A2, SLC39A3, SLC39A7, SLC39A8, SLC39A12 and SLC39A13 high expression suggested a worse OS, but SLC39A10 high expression suggested a benefit OS." (PMID 32744318, 2020).
prostate adenocarcinoma (1 paper, 2025). "The volcano plot indicated significant upregulation of genes such as SIM2, HPN, and HOXC6 in prostate adenocarcinoma (PRAD), and significant downregulation of genes such as SLC39A2, SLC39A6, and SLC39A10." (PMID 40978029, 2025).
cancer (4 papers, 2020 to 2025). A tumor composed of atypical neoplastic, often pleomorphic cells that invade other tissues. "The expression of ZIP family genes was significantly different between normal tissues and cancer tissues of different tumor grades except SLC39A2." (PMID 33869056, 2021). "SLC39A2 and SLC39A13 were found not differentially expressed between cancer tissues and normal tissues, but highly expressed of which also indicated poorer prognosis of LUAD patients." (PMID 33535184, 2021).
tumor (4 papers, 2020 to 2025). "It is noteworthy that the SLC39A2, SLC39A3, SLC39A3, and SLC39A5 showed a significant negative correlation with the macrophages and neutrophil cell infiltration in most tumor types." (PMID 34925450, 2021).
SLC39A2 also shares sentences with these, for which no sentence is quoted: hypertrophy (1 paper); myocardial infarction (1); pancreatic cancer (1).